RLIG1 (RNA 5'-phosphate and 3'-OH ligase 1)
Description:
Functions as an RNA ligase, in vitro. The ligation reaction entails three nucleotidyl transfer steps. In the first step, the RNA ligase reacts with ATP in the absence of nucleic acid to form a covalent ligase-AMP intermediate and release pyrophosphate. In step 2, the ligase-AMP binds to the nucleic acid and transfers the adenylate to the 5'-PO4 terminus to form an adenylylated intermediate. In step 3, the RNA ligase directs the attack of the 3'-OH on the 5'-phosphoanhydride linkage, resulting in a repaired 3'-5' phosphodiester and release of AMP. Exhibits selectivity for single-stranded RNA substrates and may not have nick-sealing activity on double-stranded DNA-RNA hybrids. May play a role in maintaining RNA integrity under stress conditions, for example in response to reactive oxygen species (ROS).
Synonyms: Rnl; C12orf29; DKFZp434N2030
Tractability: PROTAC: ubiquitination databases record sites on it.
Gene: Protein-coding gene on chromosome 12 (88,033,846 to 88,050,160, forward strand). Ensembl gene ENSG00000133641.
Subcellular location (Human Protein Atlas): Vesicles
Gene Ontology:
Molecular function: RNA ligase (ATP) activity
Biological process: response to reactive oxygen species
Genetic constraint (gnomAD): Loss-of-function variants: 11 observed, 17.88 expected, observed/expected ratio (o/e) 0.62, 90% interval 0.39 to 1.02. The upper end of that interval is the gene's LOEUF score, 1.02, which puts it in group 4 of 6, group 1 being the genes least tolerant of losing a copy. Missense variants: 216 observed, 234.61 expected, observed/expected ratio (o/e) 0.92, 90% interval 0.82 to 1.03. Synonymous variants: 90 observed, 77.89 expected, observed/expected ratio (o/e) 1.16, 90% interval 0.97 to 1.38.
Homologues: Orthologues: chimpanzee RLIG1 (99% identical), pig RLIG1 (90% identical), dog RLIG1 (86% identical), guinea pig RLIG1 (84% identical), mouse Rlig1 (84% identical), rat Rlig1 (84% identical), macaque RLIG1 (78% identical), rabbit RLIG1 (74% identical), zebrafish rlig1 (60% identical).
Diseases named in the same sentence as RLIG1 in open-access papers:
RLIG1 is named in the same sentence as 7 diseases in open-access papers, as found by Europe PMC text mining. Sharing a sentence is not in itself a finding about the gene and the disease. The quoted sentences say what the papers report.
cancer (2 papers, 2024 to 2025). A tumor composed of atypical neoplastic, often pleomorphic cells that invade other tissues. "The identified compounds that are synthetically lethal in combination with Rlig1-KO might be able to kill cancer cells with Rlig1 mutations that abolish its RNA ligation activity." (PMID 39211475, 2024).
RLIG1 also shares sentences with these, for which no sentence is quoted: infection (4 papers); Alzheimer disease (1); breast carcinoma (1); small cell lung carcinoma (1); tumor (1); virus infection (1).